MEN1 (menin 1)
Diseases named in the same sentence as MEN1 in open-access papers (continued):
Sharing a sentence is not in itself a finding about the gene and the disease.
tumor (continued). "The MEN1 gene encodes the menin protein, which is a scaffold protein that is involved in histone modification and epigenetic gene regulation, playing a role in tumor suppression associated with MEN1." (PMID 39371924, 2024). "The inactivation of MEN1 is often biallelic (in 40% of cases) and somatic or germline point mutations in the gene are coupled with loss of heterozygosity (LoH) at the MEN1 alleles in tumor tissue." (PMID 39456803, 2024). "Thus, currently, a family history of MEN1 remains a recognized risk factor for this neoplasia, but information on the exact genetic mechanisms is quite poor." (PMID 38294658, 2024). "The presence of two or more MEN-1-associated neoplasms was determined in 87.9% (n=94) cases." (PMID 37465121, 2023). "According to Knudson’s ‘two-hit hypothesis’, in order for a tumor to develop, a secondary event, such as large chromosomal deletions, is necessary to occur and cause biallelic inactivation of the MEN1 gene." (PMID 36428828, 2022). "However, a MEN1 mutation was recently reported in a tumor sample of TNET in a MEN1 family and also in a recent larger study of MEN1-TNETs patients." (PMID 35696052, 2022). "In addition, patients with MEN1 carry a heterozygous mutation in MEN1, and tumours arise when a second hit occurs, causing complete loss of functional menin protein." (PMID 35900839, 2022). "The researchers suggested that this may be because the MEN1 mutation is involved in tumorigenesis at an early stage in the process of tumour development." (PMID 36694894, 2022). "One of the possible causes of the variability of MEN1 tumour development could be the influence of epigenetic changes which can act as cofactors in driving individual MEN1 phenotypes." (PMID 35900839, 2022). "Combined studies of tumor linkage and microdeletions in affected families, thanks to which the gene had been localized in 1997, revealed that MEN1 patients have usually one inherited germline mutation at MEN1 locus and somatic loss of heterozygosity or point mutation in the other allele." (PMID 35268848, 2022). "MEN1 encodes menin, a putative tumor suppressor associated with multiple endocrine neoplasia." (PMID 36221106, 2022). "Numerous prognostic genomic features have been characterized as predictors of survival for pNENs, including mutations in DAXX/ATRX and MEN1, the expression levels of somatostatin receptors 2 and 5, elements of the tumor immune microenvironment, and enzymes involved in hormone metabolism." (PMID 36969744, 2022). "Since pancreatic tissues from Men1–/– but not Men1+/ΔN3-8 mice showed absence of p21Cip1 and p18INK4c expression, we asked whether the WT Men1 allele was retained in the Men1+/ΔN3-8 tumor samples." (PMID 36048542, 2022). "A heterozygous pathogenic germline MEN1 variant is insufficient to induce tumor formation and thus a somatic chromosomal loss or loss-of-function mutation (the “second hit” affecting the wild type MEN1 allele, thus causing biallelic loss) is required to cause disease." (PMID 36325452, 2022). "Furthermore, LOH studies performed on the resected tumor showed LOH in the MEN1 region involving the loss of the wild type alleles." (PMID 36325452, 2022). "In addition to menin’s role as a tumor suppressor in MEN1-associated endocrine tissues, the MEN1 gene has pro-oncogenic activity in the hematopoietic system." (PMID 35941657, 2022). "The MEN1 gene mutations are associated with tumor progression." (PMID 34207842, 2021). "However, animal models are not able to completely elucidate the exact molecular pathways involved in MEN1-associated tumor development and progression." (PMID 34769484, 2021). "Tumor lesions are characterized by somatic loss of heterozygosity (LOH) of the Men1 locus." (PMID 33919851, 2021).
tumor (continued). "In the last two decades, tissue-specific altered activity and/or expression of miRNAs have been suggested as possible modulators of MEN1 tumorigenesis, acting synergically with the MEN1 mutation, indicating the miR-24 as a possible effector of tumor development." (PMID 34298972, 2021). "Tumours in subgroup T3 harboured mutations in MEN1 (contained 30.9% of the cohort), had a higher proportion of G1 tumours (p-adj = 0.001) and a lower frequency of extra-pancreatic spread, perineural and vascular invasion, suggesting a subgroup of tumours with better prognosis." (PMID 33536587, 2021). "Since allelic deletions of MEN1 may be 2–3 times more common than MEN1 gene mutations, it has been suggested that other tumor suppressor genes on 11q13 may factor into tumorigenesis of these neoplasms." (PMID 34680266, 2021). "However, the absence of a complete genotype-phenotype correlation and the different tumor manifestations between carriers of the same MEN1 mutation (even homozygote twins) suggest that other factors concur to cause MEN1 individual tumorigenesis." (PMID 34298972, 2021). "It suggests that Men1 deficiency promotes KS tumor evade macrophage immune surveillance." (PMID 32081882, 2020). "Germinal heterozygous loss-of-function mutations of the MEN1 gene lead to the development of MEN1 tumors by following Knudson’s “two-hit” hypothesis for classical tumor suppressor genes." (PMID 33066578, 2020). "Interestingly, another gene that belongs to the P13K/mTor pathway involved in inhibiting P13K, namely PTEN, was identified as a periodically mutated tumor suppressor, which confirms previous studies on the recurrent mutation of MEN1." (PMID 31527438, 2019). "Furthermore, these tumors were noted in 35% of patients in a large cohort of pediatric patients, comprising the second most common MEN1-associated neoplasm in this group, and the first lesion identified in 21% of cases." (PMID 31263451, 2019). "These phenocopies may occur in individuals with a family history of MEN1 and one MEN1-associated tumor or in patients with two MEN1-associated tumors with other gene involvement." (PMID 31263451, 2019). "miRNAs are non-coding single-stranded RNAs that post-transcriptionally regulate gene expression and have been associated with tumour development, although the contribution of miRNAs to MEN1-associated tumourigenesis and their relationship with menin expression are not fully understood." (PMID 30389902, 2018). "MEN1 mutations have inactivating power and are consistent with a tumor suppressorgene." (PMID 29266898, 2018). "Data from our database confirmed that biochemical screenings for hormone over-production are able to anticipate the diagnosis of MEN1 of over 10 years with respect to imaging methods, for functioning tumours; radiological screenings are the only effective diagnostic method for NF-NETs." (PMID 30428914, 2018). "MEN1 gene nonsense mutations occurred in two different tumor samples." (PMID 29435419, 2018). "We also performed a stratified univariate analysis for mutations clustering to specific tumour histotypes, which showed a significant association of MEN1 mutation with poor prognosis in ACs (p = 0.0045), in which MEN1 mutations were mainly confined to early‐stage tumours." (PMID 27873319, 2017). "Consistent with Knudson’s two-hit hypothesis, theMEN1 gene is thought to act as a tumor suppressor, since over 90% of tumors from MEN1 patients exhibit loss of heterozygosity (LOH)." (PMID 28184288, 2017). "Cases 3A and 3B also both showed two frameshift mutations in the multiple endocrine neoplasia type 1 (MEN1) gene, also on chromosome 11; these variants have been previously reported as both germline and sporadic mutations in tumors of the pituitary and other sites." (PMID 27175596, 2016). "However, we identified a co-occurring somatic HRAS (p.Q61R) activating point mutation and MEN1 frameshift mutation (p.L117fs) present in a primary and recurrent tumor from one patient." (PMID 27175596, 2016).
tumor (continued). "While our immunohistochemical and exome sequencing findings point to MAPK pathway activation in SCOs, the finding of two MEN1 mutations in cases 3A and 3B suggests that biallelic inactivation of MEN1 may be a second mechanism underlying neoplasia in SCO." (PMID 27175596, 2016). "The aim of this study was to verify whether the CDKN1B V109G polymorphism is linked to aggressive tumours in MEN1 patients." (PMID 25824098, 2015). "In this study, we assessed whether the CDKN1B V109G polymorphism was associated with the development of aggressive tumours in 55 consecutive patients affected by MEN1." (PMID 25824098, 2015). "However, the potential association of MEN1 syndrome with hibernoma, a benign tumour with differentiation towards brown fat, is far less well known, despite their genetic profile both being linked to deletion of the MEN1 gene." (PMID 25309600, 2014). "According to the two-hit hypothesis of tumour development by Knudson additional somatic inactivation of the wild-type MEN-1 allele on chromosome 11q13 has to occur." (PMID 24213225, 2012). "A significant fraction of tumor samples (34%) harbored MEN1 gene variants." (PMID 22825745, 2012). "Tumors of MEN1 patients usually reveal the presence of a germline mutation followed by a somatic alteration such as loss of heterozygosity (LOH) or inactivating mutation, as predicted by the model of Knudson, pointing to MEN1 gene as a very good example of a classical tumor suppressor gene." (PMID 22567348, 2011). "Our results extend previous findings of CDKN1B mutations in patients with MEN1-related states and support the hypothesis of a tumor suppressor role for p27 in neuroendocrine cells." (PMID 20824794, 2010). "MEN1 syndrome is caused by inactivating mutations of the MEN1 tumour suppressor gene." (PMID 17014705, 2006). "Currently, DNA testing allows the early identification of germline mutations in asymptomatic gene carriers, to whom routine surveillance (regular biochemical and/or radiological screenings to detect the development of MEN1-associated tumours and lesions) is recommended." (PMID 17014705, 2006). "Furthermore, we set up a tumor driver identification strategy that could suggest first- and second-hit mutations after MEN1 loss capable of inducing aggressive PanNETs." (PMID 37270586, 2023). "Analysis of tumor tissue from a patient with MEN1 operated on twice for a thymic NET associated with the ectopic production of ACTH causing CS showed an initial Ki-67 labeling index of 5% but on re-operation the tumor was found to be invasive with a Ki-67 index of 30%." (PMID 37409236, 2023). "Following confirmation that these structural deficits were recapitulated in multiple hormone-expressing tumor cell lines, we investigated whether these clinically defined MEN1 mutations and variant confer pathogenic properties by inhibiting the tumor-suppressive function of wild-type menin." (PMID 37492626, 2023). "There is also evidence that in patients who present primary tumor alterations like MEN1 mutations, also frequently display an accumulation of these mutations in hyperplastic endocrine cells that become dysplastic and probably capable to progress into neoplasms." (PMID 36139607, 2022). "However, MEN1 is a complicated inherited disease in terms of genotype–phenotype relationship, even when an identical human MEN1 mutation was recaptured in a mouse model, whether it produces tumors and the tumor type were unpredictable." (PMID 35954231, 2022). "LOH at the MEN1 locus in tumor DNA was ascertained by Sanger sequencing of PCR products encompassing the region with germline MEN1 mutation or PCR-based analysis of blood and tumor DNA with polymorphic microsatellite markers at chromosome 11q13, using previously published or newly designed primers." (PMID 34515662, 2021). "However, in contrast with other MEN1-associated neoplasms, multiple pituitary tumors are rare." (PMID 31263451, 2019).
tumor (continued). "Heterozygous mutations in the MEN1 tumor suppressor gene is usually inherited (can also occur sporadically) and loss of the wild type allele through somatic mutations in specific organs (e.g. endocrine cells of the pancreas, parathyroid or pituitary gland) induces tumor formation." (PMID 29335487, 2018). "The clinical variability between patients carrying the same MEN1 mutation, as well as between members of the same kindred, raises the hypothesis that modifier genes and/or epigenetic tumour-predisposing events might also have a role in the pathogenesis of MEN1." (PMID 29036195, 2017). "Cytoplasmic expression of menin and presence of nucleotide variants of the MEN1 gene may be indicative of a significant correlation, since cases with MEN1 nucleotide variants are characterized by a higher number of positive tumor cells expressing menin in the cytoplasmic compartment." (PMID 22825745, 2012). "The interaction of menin with mixed-lineage leukaemia protein-containing histone methyl transferase (MLL-HMT) complex mediates tissue-selective tumour-suppressing and tumour-promoting effects and may be responsible for the tissue susceptibility to tumourigenesis in MEN-1." (PMID 21318141, 2010). "Functionally, SIRT7 inhibition enhanced radiation-induced DNA damage and apoptosis in a partially MEN1-dependent manner and significantly suppressed tumor growth in patient-derived organoids and multiple independent xenograft models." (PMID 41972414, 2026). "Screening and surveillance for MEN1‐related tumours improves outcomes, but the evidence of many individual elements is limited." (PMID 39587981, 2025). "We detected alterations in DAXX, MEN1, and ATRX, with mutations in the latter being only observed in samples extracted from primary tumor sites; these biomarkers have been shown to have prognostic significance in pancreatic NENs." (PMID 39825572, 2025). "A recent study demonstrated a novel tumor-suppressive mechanism of MEN1 through the regulation of the CD44 alternative splicing." (PMID 41369362, 2025). "MEN1 connects transcription factors and epigenetic effectors, contributing to its function as an oncogenic tumor promoter in KMT2Ar AL, NPM1m AML, and other rare AL subtypes associated with poor outcomes." (PMID 39796769, 2025). "This is further supported by experiments in Men1 knockout mouse models, where the deletion of B7x led to increased T-cell infiltration and reduced tumor burden." (PMID 40255615, 2025). "This dual pathology highlights the diagnostic challenges and the importance of considering a broad differential diagnosis in patients with MEN1, especially when encountering unusual tumor morphologies." (PMID 41155355, 2025). "Experimental studies have identified recurrent mutations in MEN1, ATRX, DAXX, TSC2, and PTEN, with MEN1 and ATRX alterations significantly associated with tumor burden in approximately 40% of cases." (PMID 40869136, 2025). "In the management of MEN1, various imaging modalities are employed to detect, monitor, and assess tumor progression." (PMID 40144450, 2025). "Multiple endocrine neoplasia type 1 (MEN1) has a tumor suppressor function and is involved in cellular proliferation, gene transcription, and genome stability." (PMID 40299639, 2025). "MEN1 patients with aggressive NF‐pNEN disease had a median tumor size of 2 cm (IQR 1.3–3.9 cm) in EUS." (PMID 40170567, 2025). "The function of the MLL gene is thought to be associated with a tumor suppressor protein called menin (from the MEN1 tumor suppressor gene), which is crucial to the leukemogenic potential of mutated MLL as it relates to HOX expression." (PMID 39200232, 2024).
tumor (continued). "To further assess the regulatory effect of MEN1 on p21 and c-myc expression in a more clinically relevant system, we also examined p21 and c-myc expression levels in resected tumor samples from preclinical MEN1 KO experiments." (PMID 38891107, 2024). "Regarding gene amplification, EWSR1, FLT3, GPC3, HIF1A, HLF, and MEN1 have been reported in CaPa and other neoplasias as well." (PMID 38397997, 2024). "To test this, we analyzed genomes from a diversity of tumor types with driver mutations in either ATM, MEN1, SETD2, BRCA1, BRCA2 and ATRX." (PMID 38909016, 2024). "Several studies have shown that most MEN1-related NF-PanNETs have an indolent course and grow slowly, with tumor growth ranging from 0.1 to 1.32 mm per year." (PMID 38893191, 2024). "In some neoplasms, MEN1 has been found to act as a hub gene, interacting with and modulating several pathways." (PMID 39201255, 2024). "The two latter genes experience two-hit inactivation in 20% of well-differentiated neoplasms analogous to MEN1." (PMID 39456803, 2024). "Here, we developed and characterized a novel PanNET mouse model based on the combined deletion of Men1, Atrx, and Pten tumor suppressors." (PMID 38609433, 2024). "Subgroup analyses for PFS were subsequently performed for baseline clinicopathological features and the presence of MEN1, DAXX, and/or ATRX mutations (seen in 19 out of 31 patients with tumor NGS available, 61.29%)." (PMID 39272851, 2024). "Further, our analysis shows that MEN1, DAXX or ATRX and PTEN mutations commonly co-occur, suggesting that combined loss of those tumor suppressors is likely a key event in pancreatic neuroendocrine cell tumorigenesis." (PMID 38609433, 2024). "Of note, we performed similar tumor burden and proliferation analyses of various combinations of Men1, Atrx, and Pten double-knockouts." (PMID 38609433, 2024). "In the MEN1/DAXXmut group, these cells exhibited a decrease from the primary (PM) to the liver metastasis (MM), both within the tumor and stroma (p = 0.205 in tumor, p = 0.075 in stroma)." (PMID 38448900, 2024). "The MEN1 phenotype varies between patients in terms of tumor localization, age of onset, and clinical aggressiveness, even between affected members within the same family." (PMID 39336996, 2024). "A recent systematic review found that the most important prognostic factors in MEN1 related NF-PanNETs were the tumor size and grade." (PMID 38893191, 2024). "Since the clinical differentiation between MEN4 and MEN1 or coincidental tumor co-occurrence is hard, molecular genetic testing is indubitably a necessity." (PMID 39194755, 2024). "Diagnosis of MEN1 typically requires the presence of a minimum of two out of the three classic tumor subtypes originating from the pituitary, pancreatic, and parathyroid glands." (PMID 39201946, 2024). "By examining resected tumor samples from our in vivo transplantation experiments, we also found that, on average, the MEN1 KO tumor samples exhibited lower caspase 3 levels than did the control tumors." (PMID 38891107, 2024). "The beta-like subtype clearly segregated from the other two subtypes, and demonstrated scarcity of MEN1/ATRX/DAXX mutations, few copy-number events and low tumor stage." (PMID 39456803, 2024). "Multiple combined tumors and tumor-like lesions with metachronous appearance complicate MEN1 diagnosis and treatment." (PMID 37867522, 2023). "Somatostatinoma is often associated in the context of familiar syndromes, including MEN1, VHL and NF1; moreover, it is a frequent tumor type in the duodenum and rare in the pancreas." (PMID 36830839, 2023). "It is therefore conceivable that MEN1 contributes to tumor survival by maintaining the activity of essential transcription factors and oncogenic signaling at a “just right” level in terms of the Goldilocks paradigm." (PMID 38003662, 2023).